TMEM235 (transmembrane protein 235)
Synonyms: ARGM1
Tractability: Antibody: UniProt predicts a signal peptide or a membrane-spanning region.
Gene: Protein-coding gene on chromosome 17 (78,231,310 to 78,240,987, forward strand). Ensembl gene ENSG00000204278.
Subcellular location: Membrane; Endoplasmic reticulum
Gene Ontology:
Cellular component: apical plasma membrane; cytoplasm; endoplasmic reticulum; membrane
Genetic constraint (gnomAD): Loss-of-function variants: 23 observed, 18.5 expected, observed/expected ratio (o/e) 1.24, 90% interval 0.89 to 1.74. The upper end of that interval is the gene's LOEUF score, 1.74, which puts it in group 6 of 6, group 1 being the genes least tolerant of losing a copy. Missense variants: 308 observed, 248.31 expected, observed/expected ratio (o/e) 1.24, 90% interval 1.13 to 1.36. Synonymous variants: 137 observed, 115.74 expected, observed/expected ratio (o/e) 1.18, 90% interval 1.03 to 1.36.
Homologues: Orthologues: chimpanzee TMEM235 (97% identical), macaque TMEM235 (89% identical), dog TMEM235 (72% identical), mouse Tmem235 (68% identical), rat Tmem235 (67% identical), zebrafish TMEM235 (40% identical), zebrafish tmem235b (37% identical). Paralogues in human: TMEM114 (41% identical).